ALDH1A2 (aldehyde dehydrogenase 1 family member A2)
Diseases named in the same sentence as ALDH1A2 in open-access papers (continued):
Sharing a sentence is not in itself a finding about the gene and the disease.
infection (7 papers, 2012 to 2025). The state of being infected such as from the introduction of a foreign agent such as serum, vaccine, antigenic substance or organism. "However, given that TB patients are likely to be systemically retinol deficient and possibility ALDH1A2 deficient at the site of infection, it is unlikely there will be abundant ATRA present." (PMID 31167948, 2019). "The IREB2, MUT, ALDH1A2, and ALDH1B1 genes formed another cluster, with MUT, ALDH1A2, and ALDH1B1 showing associations with cardiovascular disease or infection." (PMID 39194753, 2024). "Several genes involved in RA metabolic processes, which are known to be inducible by RA, were significantly downregulated in the colon of the VAS mice during peak infection, including Aldh1a1, Aldh1a2, Cyp26b1, and Lrat." (PMID 35458125, 2022). "This analysis indicates that ALDH1A2 is significantly downregulated after 2 weeks of infection but shows no change after 16 weeks." (PMID 31167948, 2019).
cardiovascular disease (3 papers, 2021 to 2024). "MUT, ALDH1A2, and ALDH1B1 are related to cardiovascular disease and metabolic pathways." (PMID 39194753, 2024).
neurodegenerative disease (2 papers, 2022 to 2024). A disorder of the central nervous system characterized by gradual and progressive loss of neural tissue and neurologic function. "ALDH1A2, a key antioxidant enzyme, has been widely reported to play a protective role in several neurodegenerative diseases." (PMID 39521994, 2024).
psychiatric disorder (2 papers, 2024 to 2025). A disorder characterized by behavioral and/or psychological abnormalities, often accompanied by physical symptoms. "As discussed in detail before, genetic studies indicate an association between ALDH1A2 and some other retinoic acid signalling genes and psychiatric disorders." (PMID 38792584, 2024).
heart disease (1 paper, 2025). "Aldehyde Dehydrogenase 1, Family Member A2 (ALDH1A2), which encodes retinal dehydrogenase 2, plays a pivotal role in synthesizing retinoic acid from vitamin A during early development and is strongly associated with heart disease." (PMID 41000338, 2025).
kidney diseases (1 paper, 2024). "We hypothesize that Aldh1a2/ALDH1A2 in PECs, through catalyzing RA biosynthesis, play important roles in kidney health, and that their dysregulation contributes to kidney disease." (PMID 39360029, 2024). "By mining the latest scRNA-seq and snRNA-seq databases of mouse and human kidneys in health and disease, we highlight glomerular PECs as the major site of Aldh1a2/ALDH1A2 expression and this expression is differentially dysregulated in different kidney diseases." (PMID 39360029, 2024). "To address this issue, we mined single-cell RNA sequencing (scRNA-seq) and single-nucleus RNA sequencing (snRNA-seq) databases to evaluate Aldh1a2/ALDH1A2 expression in different kidney cell types in mice and humans and examine how expression changes in kidney diseases." (PMID 39360029, 2024).
ALDH1A2 also shares sentences with these, for which no sentence is quoted: leukaemia (4 papers); myopia (3); amyotrophic lateral sclerosis (2); colorectal cancer (2); congenital diaphragmatic hernia (2); Tetralogy of Fallot (2); type 2 diabetes (2); adenocarcinoma (1); adenoma (1); Arrhythmia (1); arterial embolism (1); asthma (1); atherosclerosis (1); autosomal dominant polycystic kidney disease (1); brain ischemia (1); Chiari malformation type II (1); chronic kidney disease (1); coronary artery (1); COVID-19 (1); dementia (1); diabetes (1); diabetic nephropathy (1); diaphragmatic hernia (1); Dysphagia (1); endocrine system disorder (1); endometrial cancer (1); endometriosis (1); experimental autoimmune encephalomyelitis (1); focal segmental glomerulosclerosis (1); food allergy (1).
A further 30 diseases each share a sentence with ALDH1A2 in 1 paper.